FOXO1 (forkhead box O1)
Diseases named in the same sentence as FOXO1 in open-access papers (continued):
Sharing a sentence is not in itself a finding about the gene and the disease.
liver inflammation (7 papers, 2018 to 2026). "Macrophage GHSR controls inflammation and TGF‐β1 expression via protein kinase A (PKA)‐mediated Forkhead box protein O 1 (Foxo1) phosphorylation at S273; Foxo1‐S273D mutation, mimicking constitutive phosphorylation of Foxo1 at S273, shows exacerbated CCl4‐induced liver inflammation and fibrosis." (PMID 40479577, 2025). "In this study, we investigated the characteristics of the aging liver and examined the effects of FOXO1 on aging‐induced liver inflammation and glucose dysregulation." (PMID 37602516, 2023). "Inhibition of Notch signaling in obese mice (fed HFD) promotes browning of WAT, elevated expression of UCP1 in WAT, and ameliorates and transcription factor forkhead box protein O1 (FoxO1)-driven hepatic IR." (PMID 28661198, 2018). "Furthermore, the transcription factor forkhead box O1 (FOXO1) also plays a key role in regulating immune response, and is further associated with the replication of different viruses, including hepatitis B, vesicular stomatitis, and Newcastle disease viruses." (PMID 32522961, 2020).
lupus nephritis (7 papers, 2021 to 2025). Glomerulonephritis in the context of systemic lupus erythematosus. "MiR-9-5p is up-regulated in lupus nephritis (LN) patients and targets Foxo1 that is a protective factor against renal disorders." (PMID 40886372, 2025). "Recent studies demonstrated that TRIM27 was involved in the injury of glomerular endothelial cells in lupus nephritis (LN) through the FoxO1 pathway and in IgA nephropathy (IgAN) via T cell signaling." (PMID 36627639, 2023). "A previous study has shown that inhibition of miR-182 with antagomir-182 attenuated lupus nephritis in MRL/lpr mice via targeting Foxo1." (PMID 35873462, 2022). "It has been suggested that knockdown of TRIM27 inhibited the endothelial cells injuries in lupus nephritis via the FoxO1 signalling pathway." (PMID 37582060, 2022). "At the same time, another study reported that knockdown of TRIM27 could inhibit the proliferation of mesangial cells in lupus nephritis via the FoxO1 pathway." (PMID 36200036, 2022). "TRIM27 was reported to be highly expressed in the glomerular endothelial cells of patients with lupus nephritis, and TRIM27 knockdown could attenuate glomerular endothelial cell injury by regulating the FoxO1 signaling pathway." (PMID 36200036, 2022).
papillary thyroid cancer (7 papers, 2018 to 2023). "It was described that FOXO1 silencing enhances cell proliferation and decreases apoptosis of papillary thyroid carcinoma cells via Akt-FOXO1 signaling." (PMID 30413788, 2018). "In addition, previous studies showed that miR-96 played an oncogenic role in papillary thyroid carcinoma by regulating AKT/FOXO1 pathway." (PMID 34035814, 2021). "In papillary thyroid carcinoma, lncRNA ASMTL‐AS1 was reported to sponge miR‐660 to upregulate FOXO1 expression, repressing glycolysis, and tumorigenesis." (PMID 35274492, 2022).
Parkinson disease (7 papers, 2012 to 2025). A progressive degenerative disorder of the central nervous system characterized by loss of dopamine producing neurons in the substantia nigra and the presence of Lewy bodies in the substantia nigra and locus coeruleus. "Conversely, accumulating evidence implicates increased FoxO1 with Parkinson’s disease pathogenesis." (PMID 37941908, 2023). "In a study of Parkinson’s Disease, miR-182-5p and miR-183-5p were shown to mediate neuroprotection of dopaminergic (DA) neurons in vitro and in vivo by down-regulating the expression of FOXO3 and FOXO1 and enhancing PI3K-Akt signaling." (PMID 34572398, 2021).
pulmonary hypertension (7 papers, 2018 to 2025). Increased pressure within the pulmonary circulation due to lung or heart disorder. "In pulmonary hypertension models, SESN3 mediates FOXO1-induced autophagy and suppresses mTOR activity." (PMID 40507985, 2025). "Biomarker genes for pulmonary hypertension included PRKG1, KCNMA1, FOXO1, and NOS3." (PMID 35740428, 2022).
thymic lymphomas (7 papers, 2014 to 2022). "We and others previously showed that mice somatically depleted of FOXO1 along with its 2 close paralogs, FOXO3 and FOXO4, are predisposed to the development of thymic lymphomas and hemangiomas." (PMID 36282572, 2022). "Moreover, FOXO triple-knockout mice (FOXO1/3/4−/−) were prone to developing hemangiomas (endothelial cell hamartomas) and thymic lymphomas, confirming the FOXO proteins as genuine tumor suppressors." (PMID 36555288, 2022). "Interestingly, conditional triple knock-out of FOXO1/3/4 in mice results in development of thymic lymphomas and vascular lesions, predominantly haemangiomas, in a number of tissues, with only 9% progressing to angiosarcomas, although there is no reported role for Myc in this model." (PMID 31221668, 2019). "In animal experiments, mice without somatic cells of FOXO1, FOXO3a, and FOXO4 led to the progression of hemangiomas and thymic lymphomas, which proved the possible function of FOXO to serve as the redundant inhibitors of tumor growth." (PMID 29221208, 2017).
thyroid cancer (7 papers, 2019 to 2025). "In parallel with PI3K/Akt, miR-96 could synergistically amplify the FOXO1-mediated oncogenic properties in thyroid cancer." (PMID 33158279, 2020). "In thyroid cancer, IGF1-mediated activation of Akt promotes FoxO1 export from the nucleus, inhibition of FoxO1-mediated transcriptional activation of target genes like CDKN1B (p27KIP1) cell cycle inhibitor, thus promoting cell proliferation." (PMID 33673232, 2021). "miR-96 imposes its proliferative and anti-apoptotic effects via targeting Forkhead Box O1 (FOXO1), a known tumor suppressor in thyroid cancer that is phosphorylated and subsequently degraded by PI3K/Akt activation." (PMID 33158279, 2020).
triple-negative breast carcinoma (7 papers, 2021 to 2025). An invasive breast carcinoma which is negative for expression of estrogen receptor (ER), progesterone receptor (PR), and human epidermal growth factor receptor 2 (HER2). "Research has revealed elevated FOXO1 expression in DOX-resistant triple-negative breast cancer (TNBC) cells, where it maintains redox homeostasis in chemotherapy-resistant cells." (PMID 41458598, 2025). "Analysis of the mRNA expression of the FoxO family and SIRT1 in TCGA (The Cancer Genome Atlas) revealed that all genes were downregulation in tumors compared to normal tissues in TNBC (triple-negative breast cancer) (p < 0.05 for FoxO1, FoxO4)." (PMID 36142156, 2022). "Noteworthy previous studies had shown that TRIB3 promotes tumor development and resistance to therapy in triple negative breast cancer models by regulating the NOTCH pathway or the stability of SOX2 via AKT inhibition and stabilization of FOXO1." (PMID 34771470, 2021).
allergic asthma (6 papers, 2022 to 2025). A asthma with a basis in a pathological type I hypersensitivity reaction. "Our studies unravel VISTA as an immune checkpoint for ILC2 regulation via the FOXO1 pathway, presenting potential therapeutic strategies for allergic asthma by modulating ILC2 responses." (PMID 39745792, 2025). "Downstream regulators of FoxO1 represent a novel control strategy for allergic asthma and the remodeling of airway inflammation." (PMID 37987301, 2023). "Inhibition or deletion of Foxo1 can reduce IL-9 production by Th9 cells and significantly improve the inflammatory response in allergic asthma." (PMID 35935994, 2022). "Upon comparing the FoxO1 gene expression level, HDM-allergic asthma had an impact on FoxO1 gene expression that increased significantly from 1.29 ± 0.756 for the HV group to 1.822 ± 0.485 for the HDM/SCIT group." (PMID 37987301, 2023). "This study investigates the total serum IgE, FoxO1, and Sirtuin 1 (SIRT1) gene expressions in HDM-allergic asthma patients." (PMID 37987301, 2023). "Moreover, the results recommend further studies on the use of FoxO1 and SIRT1 in the treatment of HDM-allergic asthma." (PMID 37987301, 2023). "There was a negative correlation between total serum IgE levels and FoxO1 expression in HDM-allergic asthma patients whether or not they had received immunotherapy treatment." (PMID 37987301, 2023).
angiosarcoma (6 papers, 2018 to 2024). A malignant tumor arising from the endothelial cells of the blood vessels. "Mutations in the FoxO1 protein (FoxO1Ser218) can impair its ability to activate miR-34, leading to MYC overexpression and increased cell proliferation in primary cutaneous angiosarcomas." (PMID 38826780, 2024). "• aPKCλ phosphorylates FoxO1’s DNA binding domain, promoting endothelial cell proliferation and c-Myc expression.• Angiosarcoma cell growth and c-Myc expression decrease with aPKC inhibition." (PMID 38826780, 2024). "Despite an established mutual antagonism between FoxO1 and c-Myc8, 14 of 18 angiosarcoma samples showed strong FoxO1 expression, whereas FoxO1 expression in pyogenic granuloma samples was low." (PMID 30559384, 2018). "Claudin 5 is a transcriptional target of FoxO1 and a marker of angiosarcoma cells within transformed lesions." (PMID 30559384, 2018). "We observed that FoxO1 and c-Myc were highly expressed in the majority of angiosarcoma patient samples, despite known mutual antagonism between these two transcription factors." (PMID 30559384, 2018). "Our results in the angiosarcoma cell line revealed an unexpected increase in miR-34c expression and decrease in c-Myc expression and proliferation when FoxO1 was knocked down." (PMID 30559384, 2018). "Here, the authors find that aPKC lambda phosphorylates the FoxO1 transcription factor, a gatekeeper of endothelial growth, during both angiogenesis and angiosarcomas." (PMID 30559384, 2018). "Altogether the results in the angiosarcoma patient samples and cell line indicate that high aPKC expression and mislocalization, and the resulting FoxO1 phosphorylation are involved in malignant EC proliferation by controlling c-Myc expression." (PMID 30559384, 2018). "Moreover, we show that abnormal aPKC/FoxO1/c-Myc signaling contributes to excessive EC proliferation in angiosarcoma." (PMID 30559384, 2018). "Moreover, 14 of 18 angiosarcoma samples showed clear or partial nuclear localization of FoxO1 with strong protein expression." (PMID 30559384, 2018). "Interestingly, FoxO1, a transcription factor, appears to play a complex role in angiosarcoma." (PMID 38826780, 2024). "Moreover, Foxo1 phosphorylation by PKCλ contributes to cell proliferation in angiosarcoma." (PMID 32658903, 2020). "Thus, we hypothesized that the aPKCλ/FoxO1 signaling axis might be strongly activated in angiosarcoma." (PMID 30559384, 2018).
Cirrhosis (6 papers, 2018 to 2024). A chronic disorder of the liver in which liver tissue becomes scarred and is partially replaced by regenerative nodules and fibrotic tissue resulting in loss of liver function. "FoxO1 overexpression is clinically relevant considering that most patients diagnosed with HCC present with underlying cirrhosis." (PMID 38075169, 2023). "Our results support the need to continue this line of research to better elucidate the role of Akt-FoxO1 in cirrhosis." (PMID 38075169, 2023). "The confirmation of this hypothesis is of great importance since the intrahepatic levels of FoxO1 may be an indicator of individual liver regenerative capacity and, therefore, a marker with prognostic value for patients with cirrhosis and HCC." (PMID 38075169, 2023). "Therefore, Akt and FoxO1 have been proposed as promising therapeutic targets for cirrhosis and other chronic liver diseases." (PMID 38075169, 2023). "Meanwhile, ROC analysis showed that the high expression of FOXO1 could well predict the existence of HE (AUC = 0.902) and distinguish HE from cirrhosis (AUC = 0.805)." (PMID 36424620, 2022). "Genome‐wide association study (GWAS) summary statistics were extracted from seven studies (>1.7 million participants) for variants near ACVR2A, ALB, CIDEB, FOXO1, GPAM, NEAT1 and TNRC6B for: aminotransferases, liver fat, HbA1c, diagnosis of NAFLD, ARLD and cirrhosis." (PMID 35474605, 2022). "CYBB and FOXO1 might be major regulators during the development from cirrhosis to HE." (PMID 36424620, 2022). "However, it is still unclear whether inhibition of FoxO1 can reverse the development of NAFLD to NASH or even cirrhosis, which is also the direction of our efforts." (PMID 32218743, 2020).
follicular lymphoma (6 papers, 2022 to 2026). Follicular lymphoma is a form of non-Hodgkin lymphoma characterized by a proliferation of B cells whose nodular structure of follicular architecture is preserved. "In follicular lymphoma (FL), usually an indolent disease of GC centrocytes, FoxO1 mutations occur with an incidence of about 5% and up to 15% in FL transformations to DLBCL." (PMID 39533662, 2025).
Hodgkins lymphoma (6 papers, 2013 to 2025). A heterogeneous group of malignant lymphoid neoplasms of B-cell origin characterized histologically by the presence of Hodgkin and Reed-Sternberg (HRS) cells in the vast majority of cases. "Deletion of genetic loci encompassing FOXO1 was observed in only a portion of Hodgkin lymphomas, and a FOXO1 mutation accounted for 8.6% of DLBCL cases." (PMID 25909227, 2015). "In Hodgkin lymphoma or multiple myeloma, FoxO1 displays a tumor‐suppressive role as it is frequently deleted or mediates therapy‐induced cytotoxicity, respectively." (PMID 39533662, 2025). "In breast and endometrial cancers, as well as Hodgkin lymphomas FOXO1 has previously been shown to be regulated by miR-96." (PMID 24260486, 2013). "MicroRNAs may also limit their expression post‐transcriptionally, for instance, miR‐96, miR‐182, and miR‐183 repress FoxO1 in Hodgkin lymphoma, and miR‐155 represses FoxO3a in Waldenström's macroglobulinemia cells." (PMID 39533662, 2025). "Regarding the lymphoid malignancies, FOXO1 was shown to be a tumor suppressor in Hodgkin lymphoma." (PMID 25909227, 2015). "In some diseases, such as Hodgkin lymphoma or multiple myeloma, FoxO1 plays its role as a tumor suppressor and neoplasia development is characterized by a lack of FoxO1 activity." (PMID 39533662, 2025). "FOXO1 was negative in almost all classical Hodgkin lymphoma (cHL) cases and had low expression in cHL cell lines." (PMID 38714753, 2024). "B cell malignancies, with exception of classical Hodgkin lymphoma, maintain expression of FOXO1 at levels characteristic for their non-malignant counterparts." (PMID 31557894, 2019).
insulinoma (6 papers, 2016 to 2022). "As Foxo1 loss-of-function is associated with increased ALDH1A3 levels, we asked whether Foxo1 regulates ALDH1A3 in MIN6 insulinoma cells." (PMID 27572106, 2016). "The results of an in vitro trial suggested that Sirt1/FoxO1 may be one of the potential therapeutic targets for LPS‐induced oxidative stress injury in rat insulinoma cells." (PMID 35959265, 2022). "It was reported that SIRT1 regulates forkhead box O1 (FoxO1) translocation, thereby directing an anti-apoptotic transcriptional program that protects INS 832/13 cells (a rat insulinoma cell line) from nitric oxide-induced apoptosis." (PMID 35538036, 2022). "Inhibition of FoxO1 was reported to mediate the proliferative and pro‐survival effects of exendin‐4, another GLP‐1 agonist, in insulinoma cells and transgenic mice." (PMID 29524296, 2018).
myocardial infarction (6 papers, 2016 to 2024). Gross necrosis of the myocardium, as a result of interruption of the blood supply to the area, as in coronary thrombosis. "We did not observe any difference between the groups in relation to myocardial infarction area, total and phosphorylated NF-kB, total and acetylated FOXO1, SIRT1 and Nrf-2 protein expression." (PMID 31751439, 2020). "The upregulation of QKI-5 reduced the expression of FoxO1 and the stress of NS and ER in ob/ob myocardium and further reduced the injury of myocardial infarction/reperfusion." (PMID 31191799, 2019).
overnutrition (6 papers, 2019 to 2026). An imbalanced nutritional status resulting from excessive intake of nutrients. "To gain further mechanistic insight into the protective action of myeloid FoxO1 deficiency against overnutrition-induced NASH, we performed comparative liver transcriptome analysis of RNA-Seq data, detecting a total of 342 DEGs in NASH diet–fed MøFoxO1-KO versus WT littermates." (PMID 35700043, 2022). "We found that FoxO1 links overnutrition to hepatic inflammation by regulating macrophage polarization and activation." (PMID 35700043, 2022). "FoxO1 appears to be a pivotal mediator of macrophage activation in response to overnutrition and a therapeutic target for ameliorating hepatic inflammation to stem the disease progression from benign steatosis to NASH." (PMID 35700043, 2022). "Similarly, under the condition of lipotoxicity and overnutrition, the transcriptional activity of FOXO1 was increased." (PMID 31156786, 2019). "Overnutrition and age-related iron accumulation in arcuate nucleus neurons increase mitochondrial ROS production, triggering redox-dependent transcriptional reprogramming (e.g., FoxO1 activation and AgRP upregulation) and resetting hypothalamic metabolic set points." (PMID 41596490, 2026).
renal carcinoma (6 papers, 2017 to 2025). A carcinoma arising from the epithelium of the renal parenchyma or the renal pelvis. "The molecular network confirmed by IPA also showed the key involvement of miR-181a and its association with renal cancer and dysfunction directly or indirectly via JNK1, FOXO1, FOXO3, and PDCD4." (PMID 41462911, 2025). "The RNA-Seq of in vivo ibrutinib-exposed CLL cells revealed FoxO1 induction, and this attracted our attention, since FoxO1 has been shown to transcriptionally activate Rictor in renal cancer cells." (PMID 39436708, 2024). "For example, FOXO1‐H215R induced the related WNT pathway component TCF4 in renal carcinoma cells; this gene was also increased in our RNA‐Seq data by AS1842856 treatment (P = 1.25E‐38)." (PMID 37584250, 2023). "However, in colon and renal cancer cells, FOXO1 acts downstream of the PI3K/AKT signalling pathway, promoting the downregulation of MYC expression and inhibiting PD‐L1 expression." (PMID 38899748, 2024). "IPA confirmed that the target molecules identified in our study (ERK, FOXO1, FOXO3, JNK1, PDCD4, AKT3) form an interactive network with shikonin, which further leads to renal cancer, renal cell carcinoma, and apoptosis." (PMID 41462911, 2025).
renal cell carcinoma (6 papers, 2012 to 2025). "In turn, the activated AKT increased the expression of lncARSR by inhibiting the transcription factors forkhead box protein O1 (FOXO1) and FOXO3a in sunitinib-resistant renal cell carcinoma cells." (PMID 40083322, 2025).
renal fibrosis (6 papers, 2021 to 2025). A final common manifestation of a wide variety of chronic kidney diseases characterized by glomerulosclerosis and tubulointerstitial fibrosis. "HE and PAS staining showed the form of kidney beans recovered and renal fibrosis was reduced in FoxO1 treatment group, comparing to model mice group." (PMID 33473269, 2021). "In another study, intramuscular injection of exosomes with high miR-26 content prevented muscle atrophy by inhibiting FoxO1 and ameliorated renal fibrosis by suppressing connective tissue growth factor; they also demonstrated that exosomes originating at the muscle can target the kidney." (PMID 36158193, 2022). "Inhibition of β - catenin/TCF by ICG - 001 combined with TGF - β 1 treatment increased β-catenin/Foxo1 and reduced MMT and inflammatory cytokine production in bone marrow-derived macrophages, thereby attenuating renal fibrosis in the UUO model." (PMID 39445007, 2024).
acute kidney injury (5 papers, 2019 to 2025). Sudden and sustained deterioration of the kidney function characterized by decreased glomerular filtration rate, increased serum creatinine or oliguria. "In addition, we recently reported that XO inhibition attenuated contrast-induced acute kidney injury by modulating oxidative stress through the inhibition of NOX1 and NOX2, while simultaneously enhancing dephosphorylation of FoxO1 and FoxO3a." (PMID 36835220, 2023).